IL1B (interleukin 1 beta)
Diseases named in the same sentence as IL1B in open-access papers (continued):
Sharing a sentence is not in itself a finding about the gene and the disease.
gout (continued). "A combination of TLR2 ligand and urate crystals resulted in greater IL-1β secretion from gout PBMCs compared to normal PBMCs (p<0.05)." (PMID 34992596, 2021). "Based on these results, CPPD crystals act as a “danger signal” to induce IL-1β production, resulting in expansion of GMPs and in increased granulocyte/monocyte levels, and contributing to the development of gout." (PMID 33383835, 2020). "IL-1β plays a pivotal role in the initiation of gout flare, but production and release of IL-1β is a multistep process." (PMID 33488933, 2020). "The inhibition of the glycolysis pathway has been proposed as a new target for the treatment of gout flare and other IL-1β-related inflammation." (PMID 33603667, 2020). "IL-1β is the pivotal inflammatory mediator that regulates the differentiation, proliferation, and apoptosis of cells in gouty arthritis." (PMID 32382282, 2020). "Altogether, these data ascertained the s.c injection of MSU crystals in mice as an acute uratic inflammation model, highly dependent on massive IL-1β secretion, which appears to mimic human gout." (PMID 32104502, 2020). "Previous studies have demonstrated that IL-1β is an important cytokine that mediates the inflammatory response to gout." (PMID 33154749, 2020). "The current therapeutic agents used for gout treatment are nearly focused on reducing IL-1β production or blocking IL-1β-mediated signaling pathways and gene expression." (PMID 32395118, 2020). "Monosodium urate (MSU) crystal can stimulate the activation of NLRP3 inflammasome and the secretion of inflammatory cytokines such as IL‐1β, which can induce the progress of gout." (PMID 32656909, 2020). "MSU crystals are an important inducer of gouty arthritis, which is closely linked to NLRP3 inflammasome activation and mature IL-1β secretion." (PMID 33365024, 2020). "Certain diseases have been classified as an IL‐1β‐mediated condition such as gout since neutralizing antibodies to IL‐1β or the caspase‐1 inhibitor z‐YVAD significantly reduce inflammation and the production of other cytokines within the joints." (PMID 32737894, 2020). "IL-1β and IL-6 were both upregulated in the inflamed ankle tissue of gout model mice but much reduced in St2-/- mice." (PMID 33204337, 2020). "A study on gout shows that colchicine treatment significantly reduced MSU crystal-induced secretion of inflammatory cytokines (IL-1β and CXCL1) from macrophages and promoted macrophage differentiation into the anti-inflammatory M2 phenotype." (PMID 32733639, 2020). "Meanwhile, wedelolactone also significantly reduced the expression of endogenous full‐length and activated caspase‐1 (p20) and IL‐1β in the joint of MSU‐induced gouty arthritis mice." (PMID 32656909, 2020). "The concentrations of TNF-α, IL-6, IL-1β and sIgA in colon tissue (N=7/group) were notably increased in the experimental model of gouty arthritis compared with those of the normal control mice." (PMID 32670069, 2020). "Results showed that IL6 and IL-1β were significantly increased in patients with gout-derived-PMN-MDSCs compared to the control derived-PMN-MDSCs." (PMID 33154749, 2020). "Taken together, this data suggests that MDSCs are aberrantly produced in patients with gout and that PMN-MDSCs enhance the IL-1β-mediated gout inflammatory response." (PMID 33154749, 2020). "Accumulating evidence indicates that the MSU crystals-induced inflammatory responses and gout pathogenesis are dependent on interleukin (IL)-1β." (PMID 31174271, 2019). "IL-1β plays a central role in the pathogenesis of gout, in addition to the other pro-inflammatory cytokines that are produced within the tissue microenvironment during a gout attack." (PMID 31803174, 2019). "Although IL-1β production occurs in many inflammatory conditions, gout is unique in that it is primarily driven by this cytokine." (PMID 30761138, 2019).
gout (continued). "Monocytes isolated from gout patients secreted significantly greater amounts of IL-1β in response to Pam3 compared with monocytes from healthy controls." (PMID 30761138, 2019). "Studies have shown that IL-1β plays critical roles in type 2 diabetes and gout and that the blockade of IL-1β exhibits high efficacy in clinical trials." (PMID 31242947, 2019). "Because IL-1β is a pivotal cytokine in the pathogenesis of gout and its presence designates the activation of the inflammasome, we determined the role of caspase-11 in the production of IL-1β within the synovium." (PMID 31803174, 2019). "For instance, reduced inflammation was found in murine models treated with inhibitors IL-1β, and rapid clinical response to IL-1β inhibition was also observed in gout patients." (PMID 31590257, 2019). "These alternatively cleaved forms of functional IL-1β were detected in synovial fluid of a patient with inflammatory polyarthritis and gout." (PMID 31182982, 2019). "IL-1β is considered as a critical pro-inflammatory cytokine in the gout, with a wide range of systemic and local effects." (PMID 30941135, 2019). "IL-1β lies at the core of gouty inflammation, and inhibition of IL-1β release is an effective therapeutic method for gout treatment." (PMID 31590257, 2019). "MSU crystals engage the Nlrp3 inflammasome, leading to the activation of caspase-1 and production of IL-1β and IL-18 within gout-affected joints, promoting the influx of neutrophils and monocytes." (PMID 31803174, 2019). "Here, we show that caspase-11−/− mice and their derived macrophages produce significantly reduced levels of gout-specific cytokines including IL-1β, TNFα, IL-6, and KC, while others like IFNγ and IL-12p70 are not altered." (PMID 31803174, 2019). "Gout is a disease driven solely by IL-1β secretion in response to monosodium urate (MSU) crystals which form during periods of hyperuricemia and thus presents an opportunity to study factors contributing to IL-1β secretion." (PMID 30761138, 2019). "As expected, the expression of IL-1β was significantly decreased in the gout model mice with IL-33 treatment." (PMID 30863362, 2019). "The only difference in production of IL-1β was in the monocytes from gout patients in response to Pam3." (PMID 30761138, 2019). "In a model of gout, treatment with Y-27632 reduced neutrophil accumulation, IL-1β levels and hypernociception in the joint." (PMID 31450835, 2019). "It is possible that IL-1β and IL-1α are released from dead cells with the gout-inflicted joint leading to the induction of caspase-11 in an IL-1R-dependent manner, priming immune cells for inflammasome activation by subsequent insults including MSU." (PMID 31803174, 2019). "The serum level of IL-1β, an essential pro-inflammatory cytokine in the initiation and progression of gout, was examined by using an ELISA kit to investigate the anti-inflammatory effect of chicory extract on gout." (PMID 31590257, 2019). "Slides prepared from WT and caspase-11−/− mice were stained for IL-1β to examine in vivo production of this key gout cytokine within the joint space." (PMID 31803174, 2019). "Because the first production of IL-1β is of crucial importance for the development of acute gouty arthritis, we tested the ability of several specific HDAC class I inhibitors to decrease its production in PBMCs in response to a combination of C16.0 and MSU." (PMID 30728075, 2019). "Plasma concentrations of IL-1β, IL-18, IL-6, and IL-8 are elevated in the gout patients, but little is known about the role of these cytokines in the progression of gout." (PMID 31803174, 2019). "The abnormal uric acid (UA) metabolism results in monosodium urate (MSU) crystal formation in the joint and periarticular tissues, which activates the resident macrophage to produce IL-1β, a crucial inflammatory cytokines in the pathogenesis of gout." (PMID 30941135, 2019).
gout (continued). "In especially, NALP3 inflammasome matures pro-IL-1β into the active form IL-1β, which plays a key role in the development of gouty arthritis." (PMID 30914954, 2019). "Activation of the inflammasome and release of IL-1β is critical for initiating the intense acute inflammatory response in the gout flare." (PMID 30201038, 2018). "Previous studies have suggested that IL-1β acts as the central regulatory cytokine in acute gouty arthritis to recruit neutrophils into the synovium and joint." (PMID 29544526, 2018). "Neutrophil exhibit an enhanced NETs release in response to synovial fluid from gout patients, partially hindered by the IL-1β antagonist anakinra and IL-1β accelerates NETs formation triggered by MSU crystals." (PMID 30034398, 2018). "The MSU crystals, while being digested by macrophages, cause a parallel stimulation of the NLRP3 inflammasomes, thereby triggering the excessive release of IL-1β and leading to the pathogenesis of gout." (PMID 29686531, 2018). "Monosodium urate crystals activate the NLRP3 inflammasome and induce the release of active IL-1β, with a contribution of free fatty acids, which likely account for the diet-related flares of gout." (PMID 30459597, 2018). "In contrast, gout and other crystal-mediated diseases depend heavily on the activation of the innate immune system, including transduction of IL-1β signalling and PG synthesis." (PMID 29352206, 2018). "Patients with recurrent attacks of gout have been treated chronically with IL-1β-blocking therapies (anakinra, canakinumab, or rilonacept) and have significantly reduced attack rates." (PMID 30075804, 2018). "Rs45520937 of the PPARGC1B gene was associated with gout in a Chinese cohort, and the A allele of this SNP was found to significantly augment the expression of NLRP3 and IL-1β." (PMID 30123371, 2018). "IL1B rs1143623 and CD14 rs2569190 were associated with gout in a study of European and New Zealand Polynesian populations." (PMID 30123371, 2018). "It was suggested that the P2X7R/NLRP3/IL-1β pathway is involved in many inflammatory diseases including gout." (PMID 30123371, 2018). "Another study showed inhibition of serum IL‐1β alleviated gout‐related symptoms (aging‐related inflammatory disease) in monosodium urate (MSU) crystals‐induced murine model." (PMID 29045001, 2018). "The mechanism causing acute inflammation in gout patients initiates from MSU crystal deposition, and then MSU interacts with macrophages to activate NLRP3 inflammasome and IL-1β release." (PMID 29453348, 2018). "Since IL-1β is an indicator of gout inflammation, we first explored a rational MSU treatment for subsequent assays by detecting the expression of IL-1β." (PMID 29482609, 2018). "The ACP inflammatory cytokine profile was similar to that seen in gout, specifically regarding the high levels of IL1B, IL6 and IL18." (PMID 29541918, 2018). "The favorable phase I safety profile of OLT1177 combined with the reported inhibitory effects on NLRP3 inflammasome and IL-1β release led to approval of the molecule for phase II development in gout." (PMID 30075804, 2018). "In an experimental gout model, the IL-1β produced by phagocytes signals through IL-1R on the parenchymal cells, opening a systematic feedback loop of IL-1β production." (PMID 29896195, 2018). "In fact, human neutrophils incubated with Anakinra or anti-IL-1β antibody reduce the release of NETs after stimulus with serum or synovial fluid from patients with gout." (PMID 30319413, 2018). "Inflammation in acute gout attacks is characterized by the production of various pro-inflammatory cytokines such as IL-1β, IL8, and TNF-α, and the infiltration of neutrophils." (PMID 29056937, 2017). "New appreciation of the centrality of IL-1β and the inflammasome and greater insight into the transporters crucial to renal sUA handling have paved the way for the introduction of novel gout therapeutics with diverse modes of action." (PMID 28357052, 2017).
gout (continued). "Recent studies have shown that interleukin (IL)-1β is a key inflammatory mediator in acute gouty arthritis (GA), and its level is regulated by microRNAs (miRNAs)." (PMID 28915828, 2017). "For example, gout comorbidities and systemic inflammation with expression of pro-atherogenic cytokines IL-1β, IL-8/CXCL8, and IL-6 have the capacity to accelerate atherogenesis." (PMID 28818081, 2017). "Previous studies have identified polymorphisms in the NALP3 inflammasome, TLR-4, CARD8, IL-1β, IL-18, and CD14 genes to be associated with gout." (PMID 29023487, 2017). "We and others also showed that anakinra, a potent IL-1 receptor antagonist, and antibodies neutralizing IL-1β inhibit the NETosis-enhancing effect of macrophages and gout synovial fluid." (PMID 28373994, 2017). "A small but significant increase in the risk of gout has been linked with functional variants in the inflammasome component caspase activation and recruitment domain (CARD) gene CARD8, IL1B, and the TLR4 and TLR2 receptor complex co-receptor molecule CD14." (PMID 28818081, 2017). "Recently, basic and clinical research studies have implicated IL-1β and its maturation by the NLRP3 inflammasome in the pathogenesis of gout." (PMID 28167912, 2017). "Gout patients produced higher concentration of IL-1β than hyperuricemia patients following MSU + ATP stimulation." (PMID 28797095, 2017). "CD14+ cells from gout patients produced significantly higher levels of IL-1β secretion compared to cells from RA patients." (PMID 29056937, 2017). "It has been suggested that inflammasome-mediated IL-1β production in monocytic cells is responsible for the acute inflammatory response in gouty arthritis." (PMID 29056937, 2017). "MSU + ATP co-stimulated peripheral blood leukocytes in the present study, and IL-1β levels were higher in cell culture media of a patient with rs1653624 gout-sensitive genes (AA and AT) than controls." (PMID 28797095, 2017). "The MSU-induced production of IL-1β, which is mediated by the NLRP3 inflammasome activation in macrophages, is a key pathological mechanism underlying gout." (PMID 28376889, 2017). "The levels of TNF-α and IL-1β in the ankle joint lavage fluid were elevated markedly in the gouty arthritis model group when compared with the control group (P < 0.05)." (PMID 26989428, 2016). "A recent study has demonstrated that acetate mediates joint inflammation in a murine gout model through inflammasome assembly and IL-1β production that is partially FFAR2 dependent." (PMID 26963409, 2016). "Several studies have focused on the relationship between gout and candidate inflammatory genes including IL-1β, IL-6, IL-8, IL-18, and TNF-α, however, the disease pathogenesis is still not fully understood." (PMID 26890073, 2016). "It is currently unclear how the results of relatively short term expression in the FLS relate to IL-1βand pro-IL-1β levels in a condition characterised by continuing MSU exposure during gout." (PMID 25897296, 2015). "Variants rs2043211 (CARD8), rs1143623 (IL1B) and rs2569190 (CD14), which were associated with gout, are functional variations in genes directly involved in the NLRP3 signaling pathway, and as such are likely to represent genuine disease-susceptibility loci." (PMID 26462562, 2015). "IL-1β-dependent inflammation, occurring in a number of diseases in addition to gout, depends on the MSU-induced formation of a macromolecular nucleotide-binding domain-like receptor protein 3 (NLRP3) inflammasome complex." (PMID 25897296, 2015). "Nominally significant (P < 0.05) associations with gout were detected at CARD8 rs2043211 (OR = 1.12, P = 0.007), IL1B rs1143623 (OR = 1.10, P = 0.020) and CD14 rs2569190 (OR = 1.08; P = 0.036)." (PMID 26462562, 2015). "It has been established that IL-1β is a major cytokine involved in the pathogenesis of gout and is also considered a promising therapeutic target to control the inflammatory response in gout." (PMID 26347587, 2015).
gout (continued). "In recent years, with the advent of biological therapies such as anakinra, rilonacept (soluble IL-1 receptor) and canakinumab, research has focused on blocking IL-1β as a means of controlling the symptoms of gout." (PMID 25975607, 2015). "There is now compelling evidence implicating IL-1β as a key mediator of inflammation in gout, which in turn promotes the influx of neutrophils into the synovium and joint fluid." (PMID 25975607, 2015). "IL-1β is the pivotal inflammatory mediator that regulates cell proliferation, differentiation, and apoptosis in gouty arthritis." (PMID 26709520, 2015). "If this is replicated it would be consistent with an etiological role for increased IL1B expression in gout." (PMID 26462562, 2015). "Some researches had shown that inflammation and immunity played a certain role in the pathogenesis of gout, and the IL-1β level in peripheral venous blood of gout patients had significantly increased." (PMID 26557856, 2015). "IL-1β along with other pro-inflammatory cytokines, TNF-α, IL-6, and IL-8 promote neutrophil influx, the primary pathological hallmark of gout." (PMID 26709520, 2015). "AC201 is an oral IL-1β inhibitor having also uric acid-lowering effects that is under evaluation in the prophylaxis against gout flares when initiating ULT." (PMID 24839602, 2014). "In patients with gout, the pro-inflammatory cytokines such as IL-1β, IL-6 and TNF-α can reduce the synthesis and secretion of apolipoprotein in hepatocytes by affecting HMG-CoA reductase, leading to reduced levels of lipids and lipoprotein levels." (PMID 24068523, 2014). "This specific regulation can be important once IL-1β mediates a variety of local and systemic responses to infection and autoinflammatory disorders such as gouty arthritis and type II diabetes." (PMID 23690844, 2013). "Here, we report on our experience with anakinra therapy, a recombinant receptor antagonist against IL-R blocking both IL-1β and β, for gouty arthritis in a large series of patients." (PMID 24432362, 2013). "IL-1β is a major mediator of gouty inflammation and pain, and is now being increasingly evaluated for its role in acute and chronic gout." (PMID 23375025, 2013). "In particular, studies of the IL-1β-specific monoclonal antibody canakinumab for the treatment of an acute gout flare provided evidence of efficacy relative to a single intramuscular (IM) low dose of triamcinolone acetonide 40 mg." (PMID 23375025, 2013). "Recent studies suggested that MSU-mediated NLRP3 inflammasome activation and subsequent IL-1β production in macrophages as key events in initiation of gout." (PMID 22608202, 2012). "The data in the literature on IL-1β production in gout were obtained by the use of either primary mononuclear cells of healthy volunteers or human monocytic cell lines (THP-1) cells; this is the first study using cells of gout patients." (PMID 22762240, 2012). "This was proven in clinical studies, in which selective blockade of IL-1β effectively suppressed pain and inflammation in patients with gout that was refractory to other treatments." (PMID 22762240, 2012). "The production of IL-6 by MSU/C18:0 was in line with IL-1β production in cells isolated from gout patients, with a trend towards higher cytokine production in gout patients than in healthy controls." (PMID 22762240, 2012). "The present study provides evidence that the PBMCs of patients with gout display a more prominent synergistic production of IL-1β after stimulation with MSU crystals and TLR-2/1 ligands, compared to healthy controls." (PMID 22762240, 2012). "In models of gout, crystal-induced IL-1β production has been shown to be affected by Cathepsin B inhibitors that prevent lysosomal instability, and crystal-induced IL-1β production can be blocked by colchicine, a prophylactic drug for FMF patients." (PMID 23226472, 2012).